MLLT10 (MLLT10 histone lysine methyltransferase DOT1L cofactor)
Description:
Probably involved in transcriptional regulation. In vitro or as fusion protein with KMT2A/MLL1 has transactivation activity. Binds to cruciform DNA. In cells, binding to unmodified histone H3 regulates DOT1L functions including histone H3 'Lys-79' dimethylation (H3K79me2) and gene activation.
Synonyms: AF10
Tractability: PROTAC: UniProt records ubiquitination sites on it.
Gene: Protein-coding gene on chromosome 10 (21,524,617 to 21,743,630, forward strand). Ensembl gene ENSG00000078403.
Subcellular location: Nucleus
Subcellular location (Human Protein Atlas): Nucleoplasm; Cytosol
Gene Ontology:
Molecular function: chromatin binding; histone binding; nucleosome binding; protein binding; histone reader activity
Biological process: positive regulation of transcription by RNA polymerase II; chromatin organization; regulation of DNA-templated transcription
Cellular component: nucleoplasm; nucleus; protein-containing complex
Genetic constraint (gnomAD): Loss-of-function variants: 19 observed, 95.97 expected, observed/expected ratio (o/e) 0.2, 90% interval 0.14 to 0.29. The upper end of that interval is the gene's LOEUF score, 0.29, which puts it in group 1 of 6, group 1 being the genes least tolerant of losing a copy. Missense variants: 942 observed, 1,114.7 expected, observed/expected ratio (o/e) 0.85, 90% interval 0.8 to 0.89. Synonymous variants: 430 observed, 403.88 expected, observed/expected ratio (o/e) 1.06, 90% interval 0.98 to 1.15.
Cancer hallmarks: cell replicative immortality (promotes)
Homologues: Orthologues: chimpanzee MLLT10 (99% identical), macaque MLLT10 (98% identical), dog MLLT10 (96% identical), pig MLLT10 (96% identical), rabbit MLLT10 (94% identical), mouse Mllt10 (93% identical), rat Mllt10 (91% identical), guinea pig MLLT10 (85% identical), tropical clawed frog mllt10 (69% identical), zebrafish mllt10 (54% identical), Drosophila melanogaster Br140 (14% identical), Caenorhabditis elegans lin-49 (11% identical), and 1 more. Paralogues in human: MLLT6 (44% identical), BRPF3 (18% identical), BRD1 (18% identical), BRPF1 (17% identical), JADE1 (13% identical), JADE2 (13% identical), PHF14 (12% identical), JADE3 (11% identical).
Diseases named in the same sentence as MLLT10 in open-access papers:
MLLT10 is named in the same sentence as 45 diseases in open-access papers, as found by Europe PMC text mining. Sharing a sentence is not in itself a finding about the gene and the disease. The quoted sentences say what the papers report.
leukemia (61 papers, 2008 to 2026). A malignant (clonal) hematologic disorder, involving hematopoietic stem cells and characterized by the presence of primitive or atypical myeloid or lymphoid cells in the bone marrow and the blood. "Genes previously reported to be associated with leukemia have also been observed in our results to be correlated with autoimmune diseases: MLLT10 (10p12) participates in various chromosomal rearrangements associated with ALL and acute myeloid leukemia (AML)." (PMID 38616254, 2024). "For example, Mahmoudi and colleagues showed that, in cooperation with the leukemia-associated Mllt10/Af10, via H3K79 methylation DOT1L positively regulates the RNA elongation step during transcription of Wnt target genes." (PMID 35495127, 2022). "Both Brahma-related gene-1 (Brg1) and leukaemia-associated Mllt10/Af10-Dot1l are essential Tcf/β-catenin co-activators required for target gene transcription." (PMID 29570681, 2018). "A mouse knockout of the Af10-encoding gene Mllt10 has recently been generated and studied in the context of leukemia pathogenesis in adult bone marrow cells." (PMID 28931923, 2017). "Using proteomics, we identified the leukemia-associated Mllt10/Af10 and the methyltransferase Dot1l as Tcf4/β-catenin interactors in mouse small intestinal crypts." (PMID 21103407, 2010). "We thus identified the leukemia-associated Mllt10 (Af10) as an interactor of the Tcf4 complex in the crypt proliferative compartment." (PMID 21103407, 2010). "The leukemia-associated Mllt10/Af10 and its partner the histone methyltransferase Dot1l are identified as Tcf4/β-catenin co-activators and shown to be essential for Wnt-driven endogenous gene expression, intestinal development and homeostasis." (PMID 21103407, 2010). "In this study, using a proteomics approach, we identify the leukemia-associated Mllt10/Af10 and its partner the histone methyltransferase Dot1l as interactors with Tcf4/β-catenin in the mouse small intestinal epithelium." (PMID 21103407, 2010). "Finally, the lead intergenic SNP at 11q23.1 maps between C11orf53 and ARHGAP20, whereas the 10p12.31 region encompasses MLLT10 which has been linked to various leukemias, ovarian cancer, and meningioma." (PMID 30258056, 2018). "The remaining third includes four genes conserved in nematodes, fly, mouse, and human (zfp-1, R11F4.1, apl-1 and fcd-2) and whose human homologs are linked to disorders (AF10/MLLT10: leukemia, Glycerol kinase: hyperglycerolemia, APP: Alzheimer's, and FANCD2: Fanconi anemia)." (PMID 18752680, 2008). "It has already been reported that the prognosis of PICALM::MLLT10 positive T‐ALL depends on the stage of leukemia cell maturation arrest." (PMID 38895061, 2024). "In MLLT10-rearranged leukemia, DOT1L induces the transcription of genes involved in cell cycle progression (especially genes in the Homeobox A Cluster)." (PMID 36158701, 2022). "MLLT10 is one of the most common fusion partners of mixed-lineage leukemia (MLL, also known as KMT2A) in acute leukemia." (PMID 35126515, 2022). "Given the involvement of MLLT10/AF10 in Wnt target gene activation, it will be interesting to probe potential de-regulation of Wnt signaling as a consequence of the MLLT10/AF10-MLL/CALM translocation in leukemia." (PMID 21103407, 2010). "Leukemias characterized by PICALM::MLLT10 have historically been recognized to portend a poor prognosis; however, insights from larger patient cohorts provide refinement to the prognostic relevance of this chromosomal translocation, highlighting chemotherapy resistance in this leukemic subtype." (PMID 41532548, 2026). "PICALM::MLLT10 translocated leukemia is primarily an epigenetically driven disease." (PMID 41532548, 2026). "MLLT10 rearrangement is closely related to the development of leukemia." (PMID 35126515, 2022). "MLLT10/AF10 was initially identified as one of the MLL translocation partners in leukemia." (PMID 21103407, 2010).
leukemia (continued). "Thus far, studies on mammalian MLLT10/AF10 have focused on its function as a fusion partner of MLL or CALM in leukemia." (PMID 21103407, 2010). "Mature TCRγδ + PICALM::MLLT10 positive T‐ALL responds well to standard treatment, whereas TCR‐PICALM::MLLT10 positive T‐ALL has a strikingly inferior outcome, suggesting that an earlier stage of leukemia stem cells (LSCs) is insensitive and resistant to conventional therapy." (PMID 38895061, 2024). "While BMP-like leukemias harbored fusion products known to drive high HOXA cluster expression, including MLLT10, KMT2A, NUP214, and direct HOXA::TCR fusions, T-specified leukemias had fusions to ZFP36L2 (involved in cell cycle control during T-cell beta selection) and TLX1/3." (PMID 37961674, 2023). "Although the duplication of KMT2A is a rare molecular event in childhood leukemia, multiple case reports showed that patients with KMT2A::MLLT10 duplication remained in first complete remission with negative minimal residual disease at 3.5 years from diagnosis." (PMID 37942413, 2023). "Recent studies have shown that in mixed lineage leukemia, several MLL fusion partners, including MLLT10/AF10, may activate elongation of transcription by linking DOT1L to the pTEFb complex essential for transcription elongation." (PMID 21103407, 2010).
acute myeloid leukemia (19 papers, 2012 to 2024). Acute myeloid leukemia (AML) is a group of neoplasms arising from precursor cells committed to the myeloid cell-line differentiation. "The MLLT10 leukaemogenic OM-LZ domain, which induces acute myeloid leukaemia in mouse models, was maintained at the C-terminus in all the fusions." (PMID 33627125, 2021). "It is still confused whether PICALM::MLLT10 can solely correspond to acute myeloid leukemia (AML) or acute lymphoblastic leukemia (ALL) or acute leukemias of ambiguous lineage (ALAL)." (PMID 38895061, 2024). "Patient 6 (P6) M/40Y was an acute myeloid leukaemia (AML) patient with PICALM::MLLT10 fusion transcript habouring a breakpoint in PICALM exon 19 and MLLT10 exon 9 (NM_007166.4: r.-304_1944::NM_001195626.3:r.700_*1647)." (PMID 38493200, 2024). "In 2022 European LeukemiaNet (ELN) classification, PICALM::MLLT10 was identified as acute myeloid leukemia (AML) with other rare recurring translocations but not ALAL." (PMID 38895061, 2024).
acute leukemia (13 papers, 2012 to 2026). A clonal (malignant) hematopoietic disorder with an acute onset, affecting the bone marrow and the peripheral blood. "The PICALM::MLLT10 fusion gene is a rare but recurrent event in acute leukemia (AL) associated with poor prognosis." (PMID 38895061, 2024). "The 2022 WHO classification further mentioned that genomic findings such as PICALM::MLLT10 fusions are enriched in mixed‐phenotype acute leukemias (MPALs), which belong to acute leukemias of ambiguous lineage (ALAL) but need more data." (PMID 38895061, 2024). "Chromosomal translocations of the AF10 (or MLLT10) gene are frequently found in acute leukemias." (PMID 34226546, 2021). "The most frequently found fusion partners of KMT2A in acute leukemia are the C‐terminal parts of AFF1, MLLT3, MLLT1 and MLLT10." (PMID 39887730, 2026). "MLLT10 (also known as AF10) and SKIDA1 are commonly observed in acute leukemias and are indicative of a poor prognosis." (PMID 37236919, 2023).
myeloid leukemia (5 papers, 2019 to 2024). A clonal proliferation of myeloid cells and their precursors in the bone marrow, peripheral blood, and spleen. "Mutations in ATM, MGA, KMT2A, MLLT10, NSD1, and TET2 have been commonly identified in several hematological neoplasms, including both acute lymphoid and myeloid leukemia." (PMID 38672648, 2024).
endometriosis (4 papers, 2022 to 2025). The growth of functional endometrial tissue in anatomic sites outside the uterine body. "The fourth locus previously implicated and described for endometriosis and osteoarthritis is MLLT10/10p12.31, which harbours genes such as MLLT10 associated with pain perception and maintenance in multiple tissues." (PMID 40262193, 2025). "Similarly, SKAP1 and MLLT10, candidate genes for endometriosis, ovarian cancer and asthma, have also been linked to adhesion and immune regulation and hematopoietic differentiation." (PMID 37159502, 2023). "The BMI-associated variant rs7084454 (intronic to MLLT10) was shared by substantial clusters for PCOS, endometriosis, and UF, while rs114760566 (mapped to HMGA1, associated with type 2 diabetes and multiple lipomatosis) was shared by endometriosis and UF." (PMID 35104295, 2022). "The clustering analysis, which reveals pain-related genes (SRP14/BMF, GDAP1, MLLT10, BSN, and NGF), further solidifies the genetic basis for the chronic and often debilitating pain experienced by patients with endometriosis." (PMID 41516028, 2025). "eQTL analyses highlighted genes affected by shared risk variants, enriched for seven pathways across all four conditions, with three genetic loci shared between endometriosis and osteoarthritis (BMPR2/2q33.1, BSN/3p21.31, MLLT10/10p12.31) and one with rheumatoid arthritis (XKR6/8p23.1)." (PMID 40262193, 2025).
meningioma (4 papers, 2013 to 2024). A generally slow growing tumor attached to the dura mater. "At present, most of research about the MLLT10 gene is about disease, and it has been verified that the MLLT10 gene variation at 10p12.31 near MLLT10 influences meningioma risk." (PMID 32033330, 2020). "As early as 2011, a sequencing-based genome-wide association study (GWAS) of 859 patients with meningioma and a control group (n = 704) identified MLLT10 as a new susceptibility locus." (PMID 32983987, 2020). "A genome-wide association study including 859 meningioma patients and 704 control subjects identified the MLLT10 gene as strongly associated with susceptibility to meningiomas." (PMID 23349797, 2013). "It is worth mentioning that, in the last decades, the role of MLLT10 in the pathogenesis and progression of meningioma has been well-established." (PMID 32983987, 2020). "The MLLT10 gene is located at 10p13 and most research is currently on the study of leukemia and meningioma." (PMID 32033330, 2020).
T-cell acute lymphoblastic leukemia (4 papers, 2014 to 2023). Acute lymphoblastic leukemia of T-cell origin. "DDX3X is one of the partners of MLLT10 in adult and paediatric T-cell acute lymphoblastic leukaemia (T-ALL)." (PMID 33627125, 2021). "In T-cell acute lymphoblastic leukaemia (T-ALL), the fusion of DDX3X with MLLT10 preserves the N-terminus of DDX3X, which contains the NES and eIF4E binding site." (PMID 33627125, 2021).
breast carcinoma (3 papers, 2020 to 2024). "MLLT10 is one of the breast cancer susceptibility loci identified by genome wide association studies." (PMID 32139710, 2020). "In the analysis of the correlation between overall survival and significant DEG expression (CLDN7, MLLT10, RBM33, SH3RF1, SSBP4, and UBE2Z) in breast cancer, we found a shorter survival time based on GSE5881 and GSE42568 (P< 0.05)." (PMID 34151730, 2021). "Significantly overexpressed genes (CLDN7, MLLT10, RBM33, SH3RF1, SSBP4, and UBE2Z) were correlated with shorter survival, whereas underexpressed genes (BMPER, FGF7, MSRB3, and TNRC6B) were correlated with longer survival in breast cancer." (PMID 34151730, 2021). "The non-pseudo gene version of MLLT10 has been documented to be a promoter of tumor cell proliferation, migration, and invasion in NSCLC cell lines, and MLLT10P1 is commonly mutated in breast cancer patients." (PMID 38797520, 2024). "Interestingly, other DEGs in breast cancer identified in this study, including MLLT10, RBM33, SH3RF1, UBE2Z, and TNRC6B, have not been proven in previous studies." (PMID 34151730, 2021).
colorectal cancer (3 papers, 2010 to 2022). A primary or metastatic malignant neoplasm that affects the colon or rectum. "The leukemia-associated protein, Mllt10/Af10-Dot1, is identified as another component of the β-catenin-TCF transcriptional complex in colorectal cancer to promote transcription elongation." (PMID 28430641, 2017). "Depletion of MLLT10/AF10 in colorectal cancer and Wnt-inducible HEK293T cells followed by expression array analysis identifies MLLT10/AF10 and DOT1L as essential activators to a large extent dedicated to Wnt target gene regulation." (PMID 21103407, 2010). "To examine the specificity of MLLT10/AF10 in Wnt transcriptional regulation, we performed microarray analysis in Ls174T colorectal cancer cells comparing the effect of MLLT10/AF10 depletion with two other known Wnt coactivators, BRG1 and p300." (PMID 21103407, 2010). "Mllt10/Af10-Dot1l, essential for transcription elongation, are recruited to Wnt target genes in a β-catenin-dependent manner, resulting in H3K79 methylation over their coding regions in vivo in proliferative crypts of mouse small intestine in colorectal cancer and Wnt-inducible HEK293T cells." (PMID 21103407, 2010).
autism spectrum disorder (1 paper, 2020). A spectrum of developmental disorders that includes autism, and Asperger syndrome. "In the patient with a BCT disrupting MLLT10 and TLE3, it is unclear which gene is responsible for the phenotype, nevertheless both genes have few possibly pathogenic variants reported in humans (all linked to autism spectrum disorder) and none of them are similar to the proband phenotype." (PMID 32344861, 2020).
autoimmune disease (1 paper, 2024). A disorder resulting from loss of function or tissue destruction of an organ or multiple organs, arising from humoral or cellular immune responses of the individual to their own tissue constituents. "While direct evidence for the impact of MLLT10 on autoimmune diseases has not been established, studies indicated a close association with C-reactive protein levels, widely recognized as a valuable indicator of disease activity in various autoimmune rheumatic diseases." (PMID 38616254, 2024).
colon tumor (1 paper, 2010). "MLLT10/AF10 was also highly expressed in human colon tumor samples." (PMID 21103407, 2010).
lymphoid leukemia (1 paper, 2022). A malignant lymphocytic neoplasm of B-cell or T-cell lineage involving primarily the bone marrow and the peripheral blood. "Studies have shown that MLLT10 is often observed in acute myeloid and lymphoid leukemia, affecting its treatment and prognosis." (PMID 35126515, 2022).
microphthalmia (1 paper, 2023). Congenital or developmental anomaly in which the eyeballs are abnormally small. "A similar search of DR17 using the term microphthalmia resulted in 22 genes significant for the small eyes phenotype: Aldh1a3, Aff4, Bmp4, Cdk4, Cox6b1, Cxcr4, Dync1li1, Eef1d, Fgd1, Gne, Grh12, Mab21l2, Maf, Med13l, Mllt10, Mthfd2, Pex6, Phgdh, Ssr1, Stim1, Tdo2, and Vps26c." (PMID 36737727, 2023).
migraine (1 paper, 2024). "Besides, the expression of MLLT10 was associated with pain perception/maintenance, including migraine, the occurrence of which was closely related to PFO." (PMID 39872005, 2024).
Myelodysplasia (1 paper, 2020). Clonal hematopoietic stem cell disorders characterized by dysplasia (ineffective production) in one or more hematopoietic cell lineages, leading to anemia and cytopenia. "AML with myelodysplasia‐related changes, GATA2, and MLLT10 abnormalities were detected in other six patients, respectively." (PMID 35847688, 2020).
non-small cell lung carcinoma (1 paper, 2022). A group of at least three distinct histological types of lung cancer, including non-small cell squamous cell carcinoma, adenocarcinoma, and large cell carcinoma. "Previous studies have shown that inhibition of MLLT10 expression can affect the proliferation, migration, and invasion of non-small cell lung cancer cells." (PMID 35126515, 2022). "Meanwhile, MLLT10 might be involved in the metastasis of non-small cell lung cancer." (PMID 35126515, 2022).
osteoarthritis (1 paper, 2025). A noninflammatory degenerative joint disease occurring chiefly in older persons, characterized by degeneration of the articular cartilage, hypertrophy of bone at the margins and changes in the synovial membrane. "Specifically, three SNPs were shared with osteoarthritis (BMPR2/2q33.1, BSN/3p21.31, and MLLT10/10p12.31), and one was shared with both osteoarthritis and rheumatoid arthritis (XKR6/8p23.1)." (PMID 40262193, 2025).
T-cell leukemia (1 paper, 2022). A malignant disease of the T-lymphocytes in the bone marrow, thymus, and/or blood. "Myeloid/lymphoid or mixed-lineage leukemia translocated to 10 (MLLT10) is a putative transcription factor that commonly presents as a gene fusion product with clathrin assembly lymphoid myeloid (CALM) in T-cell leukemia." (PMID 36077609, 2022).
cancer (10 papers, 2013 to 2025). A tumor composed of atypical neoplastic, often pleomorphic cells that invade other tissues. "Other cancer genes detected in focal CNV peaks included EGFR (7p11.2 amplification), MDM2 (12q15 amplification), CCND1 (11q13.3 amplification), and MLLT10 (10p12.31 amplification), which were also enriched in TETs." (PMID 41388389, 2025). "Some of the most prevalent included known pediatric cancer fusions RUNX1::RUNX1T1 (15% AML participants), KMT2A::MLLT3/MLLT10 (12% AML), TCF3::PBX1 (4.4% ALL), and ETV6::RUNX1 (2.4% ALL)." (PMID 37323575, 2023). "In Pt2, five integrations with total frequencies of more than 1% were observed near or in cancer-related genes (DPP4, TNFAIP3/PERP, MLLT10, EPS8, and SPINT1)." (PMID 34786435, 2021). "In addition, transcriptional regulation of cancer pathways, such as transcriptional misregulation in cancer (ecb05202, e.g., MYC, MLLT10) and microRNAs in cancer (ecb05206, e.g., MIR125B), were enriched." (PMID 36553455, 2022).